ALDH1A3 (aldehyde dehydrogenase 1 family member A3)
Diseases named in the same sentence as ALDH1A3 in open-access papers (continued):
Sharing a sentence is not in itself a finding about the gene and the disease.
cancer (continued). "Previous studies suggest that ALDH1A3 is closely associated with the colony formation, sphere formation, tumorigenesis, and angiogenic activity of cancer cells." (PMID 32612951, 2020). "Remarkably, USP22 knockout had pronounced effects on expression of these important cancer-associated gene sets such as c-Myc, E2F, and selected genes including ALDH1A3, CCNE1/G1, E2F6, HOXA1, MMP9, NFKB2, TP63, TPM4, SET7/9 were validated by qRT–PCR." (PMID 31842906, 2019). "Changes in the ALDH1A3 isoform is interesting, as this isoform has been linked to many other cancer types and often follows the same pattern of ALDH1A1." (PMID 28280782, 2015). "Specifically, expression changes in SNAI1, CD44 and ALDH1A3 genes were positively associated with the viable cancer cell fraction (rs > 0.5 and p < 0.05), suggesting that PDS cultures promoting CSC features might be less susceptible to T cells action." (PMID 40240529, 2025). "ALDH1A3 expression has been associated with worse survival outcomes in a variety of cancers." (PMID 37047661, 2023). "Unsurprisingly, the effects of ALDH1A3 in cancer have been linked to RA in multiple studies." (PMID 36672441, 2023). "Finally, we surveyed the available patient tumor datasets for cBioportal in cancers that ALDH1A3 has been implicated in tumor progressions for potential mutation mechanisms leading to changes in gene expression." (PMID 36672441, 2023). "Increasing evidence indicates ALDH1A3 as an important molecule that influences a diverse range of biological processes in CSCs and in tumor cells, thereby being associated with the initiation, progression, and prognosis of various cancers including GBM." (PMID 32680476, 2020). "According to the circRNA target profiling and pathway enrichment analysis, the high‐confidence DECs could influence the expression of cancer stem cell‐associated core signature genes such as ALDH1A3, SOX9, CD109, LIF and BMPR1 via negative regulation of miRNAs." (PMID 35579852, 2022). "CLM296 shows no observable toxicity in preclinical models, supporting its potential as a first-in-class ALDH1A3 inhibitor for ALDH1A3-positive cancers." (PMID 41797928, 2026). "Here, we resolve this paradox by showing that cancers with ALDH1A3 activity concomitantly lose sensitivity to atRA." (PMID 41210994, 2025). "Recent studies have found that the high expression of ALDH1A3 in some tumors is closely related to the maintenance and radiotherapy resistance of cancer stem cells (CSCs)." (PMID 40227735, 2025). "Overall, these results suggest that senescent cells knocked down by ALDH1A3 inhibit the promoting effect of SASP on cancer progression." (PMID 40227735, 2025). "We show that this mechanism is exploitable in cancer as blockade of retinoic acid production by inhibiting cancer cell-expressed ALDH1A3 allows Th17 T cell expansion while suppressing Th2 T cells." (PMID 41210994, 2025). "We resolve this paradox by showing that while ALDH1A3 is overexpressed across diverse cancers, ALDH1A3-expressing tumor cells lose sensitivity to retinoid signaling." (PMID 41210994, 2025). "Tumor growth measurements demonstrated that ALDH1A3 knockout had a minimal effect on primary tumor growth in each cancer type, with replicates showing low variability across repeated experiments." (PMID 41210994, 2025). "In line with our findings, ALDH1A3 is known as a metabolic target for cancer diagnosis and therapy across different tumor types." (PMID 40781158, 2025). "Due to inherent limitations imposed by the human-specific development criteria, the early experiments on ALDH1A3 knockouts in human cancer cell lines were conducted in immunocompromised NSG mice." (PMID 41210994, 2025). "Using these selective inhibitors as a unique research tool, we show that ALDH1A3 oxidizes all-trans retinaldehyde into atRA in cancer cells that works as a paracrine factor to suppress anti-tumor T cell immunity." (PMID 41210994, 2025).
cancer (continued). "Here, we utilized genetic approaches to assess the importance of ALDH1A enzymes to atRA formation in human cancers and show that ALDH1A3 is specifically enriched in certain human cancers to create atRA." (PMID 41210994, 2025). "To determine the breadth of ALDH1A3 activity across human cancers and assess the target engagement of these discovered compounds across tumor models, we profiled a panel of 23 human cancer cell lines with the Aldefluor assay." (PMID 41210994, 2025). "ALDH1A3 specifically converts all-trans-retinal to retinoic acid, impacting physiological processes and cancer stem characteristics, suggesting it as a potential marker for these cells." (PMID 40334012, 2025). "Expression and prognosis studies have further shown that ALDH1A3 is strongly predictive of poor outcomes across cancer types." (PMID 41210994, 2025). "ALDH1A3, a member of the aldehyde dehydrogenase family, is believed to play an important role in glycolysis and cancer cell metabolism." (PMID 40227735, 2025). "Next, we evaluated the effect of the SASP components secreted by senescent cells induced by ALDH1A3 knockdown on cancer cell migration using a scratch assay." (PMID 40227735, 2025). "ALDH1A3 has been targeted in the current study due to its broad-spectrum implication in various types of cancer indicating its elevated expression as target for anticancer drug development." (PMID 40887554, 2025). "Specific ALDH1 isoforms, such as ALDH1A1 and ALDH1A3, are highly expressed in certain cancer cell subpopulations that exhibit stem cell-like characteristics and are resistant to chemotherapy and radiotherapy." (PMID 39781359, 2025). "Here, we assessed if this immunological function of ALDH1A3 is preserved in human cancers by replicating this mechanistic approach in a human solid cancer model using CD34-humanized mice." (PMID 41210994, 2025). "Secondly, how ALDH1A3 affects other key cancer-related pathways through the cGAS–STING pathway remains to be further explored." (PMID 40227735, 2025). "Targeting ALDH1A3 with a selective inhibitor and short hairpin RNA has the potential to reduce cancer cell stemness, migration, and invasiveness, making it a promising approach in cancer therapy." (PMID 39781359, 2025). "The cancer stem cell marker aldehyde dehydrogenase 1A3 (ALDH1A3) is a critical enzyme in acetaldehyde metabolism, but the interconnection to the basal-like subtype is poorly understood." (PMID 40781158, 2025). "Additional deletion of Rb in this line did not induce accelerated cell proliferation but did induce the expression of a cancer stem cell marker aldehyde dehydrogenase 1A3 (ALDH1A3), and higher spherogenic activity." (PMID 40707487, 2025). "In HCC1806 cells, we found tumor growth effects in line with other studies of ALDH1A3 in cancer, where ALDH1A3 knockdown reduces tumor growth (as per tumor volumes and tumor weights, center)." (PMID 39251846, 2024). "ALDH1A3 is an important player in the progression of several other cancers, hence it will be crucial to evaluate if ALDH1A3 regulates the plasminogen activation pathway in these cancers as well." (PMID 37753740, 2024). "We found that aldehyde dehydrogenase 1A3 (ALDH1A3) regulates these cancer-promoting processes and the abundance of the two distinct breast CSC populations defined by high ALDH activity and CD24−CD44+ cell surface expression." (PMID 39251846, 2024). "We were especially curious in the case of the MDA-MB-468 cells, which is an atypical cell line with respect to the effects of ALDH1A3 on tumor growth; to our knowledge, it is the only reported cancer cell line in which ALDH1A3 knockdown promotes tumor growth." (PMID 39251846, 2024). "ALDH1A3's cancer‐promoting activities in TNBC are least in part related to its generation of ATRA and subsequent gene expression changes, although how these gene expression changes affect its invasion and metastasis‐promoting function is unclear." (PMID 37753740, 2024).
cancer (continued). "We also review the recent attempts to develop both ALDH1A3-selective inhibitors for cancer therapy and ALDH1A3-specific fluorescent substrates for fluorescence-guided tumor resection." (PMID 39001459, 2024). "CCAAT enhancer binding protein beta (CEBPβ) binding to a CAAT box in the ALDH1A3 promoter is responsible for the overexpression of the ALDH1A3 gene in several cancer cells." (PMID 39001459, 2024). "ALDH1A3 is overexpressed in various cancers and is a marker of cancer stem cells, which contributes to cancer initiation, metastasis, therapeutic resistance, and relapse." (PMID 38669046, 2024). "Specifically, ALDH1A3high cancer cells that existed before drug treatment were selected after drug exposure or drug treatment induced ALDH1A3-overexpressing cells." (PMID 38669046, 2024). "We also illustrate the current attempts to develop ALDH1A3-selective inhibitors and specific fluorescent probes that are potentially useful for cancer therapy and fluorescence-guided tumor resection." (PMID 39001459, 2024). "Drug discovery in cancer research has thus far been applied to ALDH1a1, ALDH1a3, and ALDH3a1 while drug discovery in substance abuse has focused on ALDH2, and discovery in the male contraceptive space has focused on ALDH1a1/a2 or RARα." (PMID 39133222, 2024). "The presence of ALDH1A3-positive cancer stem cells is also instrumental in maintaining hypervascularization of the stem cell niches by paracrine release of plasminogen activator inhibitor-1 and interleukin-8, which stimulate neovasculogenesis." (PMID 39001459, 2024). "Herein, we review the role of ALDH1A3 in cancer, showing its relation with excessive proliferation, chemoresistance, and invasiveness." (PMID 39001459, 2024). "Because ALDH1A3 is a normal stem and cancer stem cell marker, these results suggest that breast epithelial cells in the normal breasts of BRCA1 mutation careers have inherently higher stem cell activity." (PMID 38059556, 2024). "Investigations into the function of ALDH1A3 in cancer suggest it promotes disease progression by both increasing tumour burden and metastasis." (PMID 37753740, 2024). "The paracrine immune mechanism of atRA also explains why ectopic expression of ALDH1a2 or ALDH1a3 in ALDH-negative cancer cells is often growth suppressive." (PMID 39133222, 2024). "In these studies, knocking down or inhibiting ALDH1A3 sensitized the cancer cells to the chemotherapies, illustrating that ALDH1A3 mediates chemoresistance in cancer." (PMID 36672441, 2023). "Multiple studies have demonstrated that ALDH1A3 is an ALDH isoform that is at least as important as ALDH1A1 in influencing the Aldefluor activity of cancer cells." (PMID 36672441, 2023). "There are many reports of ALDH1A3 affecting invasion and/or migration, but these effects appear cancer-type dependent." (PMID 36672441, 2023). "Specifically, ALDH1A3 is highly expressed in drug resistant cancer stem cells (CSCs), characterized by the capability to promote self-renewal, clonogenic growth and metastases." (PMID 37047661, 2023). "Increasing evidence has shown that ALDH1A3 exhibits high activity in multiple cancer types and influences a diverse range of biological characteristics including cell proliferation, invasion, therapy resistance and prognosis." (PMID 36996494, 2023). "The accumulating evidence of ALDH1A3 as a key factor in cancer progression across multiple cancer types suggests it is a promising therapeutic target." (PMID 36672441, 2023). "Aldehyde dehydrogenase 1A3 (ALDH1A3) is the primary cause of the high ALDH activity associated with cancer stem cell (CSC) populations in multiple cancers and its expression promotes cancer progression." (PMID 36672441, 2023). "Cancer stem cell markers were also examined, which showed an upregulation in ALDH1A3, CD44, and WNT5A in amoeboid cells, and increased SOX2 and BMI1 in escaping cells." (PMID 37575281, 2023).
cancer (continued). "CSCs also display altered energetics, and evidence suggests that ALDH1A3 plays a part in the metabolic reprogramming of cancer." (PMID 36672441, 2023). "Since then, interest in investigating the roles of ALDH1A3 in cancer, and the potential of targeting ALDH1A3, have grown exponentially." (PMID 36672441, 2023). "The fact that ALDH1A3 knockdown sensitizes cancer cells to therapy further supports the need for the development of clinical ALDH1A3 inhibitors as adjuvant therapies (discussed later in this review)." (PMID 36672441, 2023). "Together, the published studies and dataset analysis suggest that ALDH1A3 expression dysregulation in cancer is multifactorial and mediation by genetic, epigenetic, post-transcriptional, and post-translational mechanisms." (PMID 36672441, 2023). "Generalities that arose from our ALDH1A3 literature review suggest it has pro-tumor growth and metastatic effects in cancer." (PMID 36672441, 2023). "Increasing evidence has revealed a strong connection between the aldehyde dehydrogenase family member ALDH1A3 and tumorigenesis, therapy resistance, and prognosis in diverse types of cancer." (PMID 37551838, 2023). "We review the role of ALDH1A3 in normal physiology, its identification as a cancer stem cell marker, and its modes of action in cancer and other diseases." (PMID 36672441, 2023). "Growing evidence has shown that ALDH1A3 participates in various biological processes, including development, progression, and therapy resistance in multiple types of cancer." (PMID 37551838, 2023). "Mechanism studies suggest that ALDH1A3-mediated cancer progression and chemoresistance are, in general, due to ALDH1A3-mediated gene expression effects." (PMID 36672441, 2023). "ALDH1A3 also induces gene expression changes indirectly or independently of RA, leading to effects in cancer." (PMID 36672441, 2023). "In a report, including 58 human cancer cell lines, the ALDH1A3 mRNA expression is positively related to its ALDEFLOUR activity, implying that ALDH1A3 is one of the predominate ALDH isoenzymes to maintain the ALDHbright populations." (PMID 36694633, 2023). "Increased expression of the resistance genes ABCG2 and ERBB2, the CSC gene ALDH1A3, as well as the EMT gene SNAI1 after 5-FU treatment in PDSs were linked to ER-negative status of the primary cancer." (PMID 38124067, 2023). "ALDH1A3 in particular is known for its role in catalyzing the reaction responsible for retinoic acid synthesis, crucial for embryonic and cancer development." (PMID 37511575, 2023). "The increased levels of ALDH1A3 in cancer occur due to genetic amplification, epigenetic modifications, post-transcriptional regulation, and post-translational modification." (PMID 36672441, 2023). "In contrast to direct effects on drug metabolism, we observe cell signaling mediated effects by ALDH1A3 in cancer cells leading to MDR." (PMID 36672441, 2023). "Here, ALDH1A3 was again being used to remark enrichment of drug-tolerant persister cancer cells, cisplatin resistance, and quiescent population resembling diapause state." (PMID 36982384, 2023). "ALDH1A3 is often over-expressed in cancer and promotes tumor growth, metastasis, and chemoresistance by altering gene expression, cell signaling pathways, and glycometabolism." (PMID 36672441, 2023). "The downregulation of ALDH1A3 in response to KDM5D silencing also suggested the role of the KDM5D/AURKB axis in modulating ALDH1A3-mediated cancer stemness, platinum tolerance, and transition towards the quiescent state of HNSCC cells." (PMID 36982384, 2023). "The possibility of inhibiting ALDHs and ALDH1A3 specifically in the treatment of cancer and targeting of CSCs has also been investigated in recent years by various drugs." (PMID 36672441, 2023). "Complementing the extensive transcriptomics previously completed on ALDH1A3-expressing cancer cells with metabolomics is a potential strategy to identify pro-metastatic pathways that are not obvious by gene expression data alone." (PMID 34989902, 2022).
cancer (continued). "With this paper, we describe new possible selective probes that are able to detect ALDH1A3 in GBM cancer cells." (PMID 36050388, 2022). "ALDH1A3 is a known marker of cancer stem cells which has been shown to be important for the proliferation, migration, and maintenance of the mesenchymal cancer stem cell phenotype." (PMID 36275636, 2022). "Cancer tissues of HCC patients with higher expression of lncMMPA displayed higher levels of ALDH1A3, and vice versa, in ZSHS cohort 1 and TCGA LIHC dataset." (PMID 35986343, 2022). "Herein, we instead examine the pro-metastasis and cancer progression mechanisms of ALDH1A3 beyond its function in gene expression regulation; the effects of the enzyme on metabolites." (PMID 34989902, 2022). "ALDH1A3’s cancer-promoting activities are least in part related to its generation of retinoic acid and subsequent gene expression changes." (PMID 34989902, 2022). "The ALDH1A3 isoform has recently elicited wide interest because of its potential use as a cancer stem cell biomarker and drug target." (PMID 35418200, 2022). "ALDH1A3 (Aldehyde Dehydrogenase 1 Family Member A3) catalyzed the formation of retinoic acid and played roles in a diverse range of biological characteristics within cancer stem cells." (PMID 36147494, 2022). "Attenuation of ALDH1A3 expression by RNA interference (RNAi) significantly suppressed cell proliferation, reduced the number of cancer cells that persisted after anticancer treatment and interfered with tumor growth in a mouse xenograft model." (PMID 35299840, 2022). "It has been reported that LoVo-1 and K1 cells with high expression of ALDH1A3 were resistant to the focal adhesion kinase autophosphorylation inhibitor Y15, while cancer cells with low ALDH1A3 level showed high sensitivity to Y15." (PMID 35831872, 2022). "In this paper, we present the first highly potent and selective ALDH1A3 inhibitor able to induce cytotoxic effects and to reduce cell migration and stemness of ALDH1A3-positive cancer cells." (PMID 33478031, 2021). "ALDH1A3 has been highlighted as a promising target for cancer treatment and is recognized as a CSC marker." (PMID 33478031, 2021). "Recent studies have shown that ALDH1A3 was required for sustaining ALDH activity in cancer stem cells 27 and was also regarded as a key determinant for the maintenance of mesochymal features of GSLCs." (PMID 33403039, 2021). "ALDH1A3 (Aldehyde dehydrogenase 1 family member A3) an isozyme metabolizes aldehydes to their respective carboxylic acid and is higher expressed in the cancer stem cell niche of GBM and other cancers." (PMID 35008722, 2021). "Several studies have reported ALDH1A3 overexpression in different cancer types, which has been found to correlate with poor treatment recovery." (PMID 34641313, 2021). "In human cancers, ALDH1A1 and ALDH1A3 have been found to be increased and correlated with some parameters of cancer staging, the ability of cancer cells to form metastases, and the onset of resistance to chemotherapeutic drugs." (PMID 34943045, 2021). "In order to confirm the importance of ALDH1A3 in the survival of cancer cells, we evaluated the cellular growth through MTT assay, after transfection with #84 (and #85)." (PMID 33478031, 2021). "Aldehyde dehydrogenase 1A3 (ALDH1A3) has recently gained attention from researchers in the cancer field." (PMID 34641313, 2021). "Hydrogen peroxide also elevates the detoxification enzyme and cancer stem cell marker aldehyde dehydrogenase 1 family member A3 (ALDH1A3)." (PMID 33411704, 2021). "Taken together all this data confirm the relevant role of human ALDH1A3 on cancer cell maintenance and tumour progression." (PMID 33478031, 2021). "We propose the targeting of the ALDH1A3 enzyme as a promising approach for improving the treatments outcomes of patients affected by ALDH1A3-positive cancers." (PMID 33478031, 2021).